SHISA9 (shisa family member 9)
Description:
Regulator of short-term neuronal synaptic plasticity in the dentate gyrus. Associates with AMPA receptors (ionotropic glutamate receptors) in synaptic spines and promotes AMPA receptor desensitization at excitatory synapses (By similarity).
Synonyms: CKAMP44
Tractability: Antibody: UniProt predicts a signal peptide or a membrane-spanning region; its Gene Ontology location is reachable by antibodies, with medium confidence. PROTAC: its protein half-life has been measured.
Gene: Protein-coding gene on chromosome 16 (12,901,598 to 13,240,416, forward strand). Ensembl gene ENSG00000237515.
Subcellular location: Cell projection, dendritic spine membrane; Synapse
Subcellular location (Human Protein Atlas): Cytosol; Vesicles
Gene Ontology:
Molecular function: PDZ domain binding
Biological process: regulation of short-term neuronal synaptic plasticity
Cellular component: AMPA glutamate receptor complex; dendritic spine membrane; ionotropic glutamate receptor complex; postsynaptic density; postsynaptic membrane; synapse; glutamatergic synapse; postsynaptic density membrane
Genetic constraint (gnomAD): Loss-of-function variants: 13 observed, 36.04 expected, observed/expected ratio (o/e) 0.36, 90% interval 0.23 to 0.57. The upper end of that interval is the gene's LOEUF score, 0.57, which puts it in group 2 of 6, group 1 being the genes least tolerant of losing a copy. Missense variants: 538 observed, 574.46 expected, observed/expected ratio (o/e) 0.94, 90% interval 0.87 to 1.01. Synonymous variants: 275 observed, 246.68 expected, observed/expected ratio (o/e) 1.11, 90% interval 1.01 to 1.23.
Homologues: Orthologues: chimpanzee SHISA9 (100% identical), macaque SHISA9 (99% identical), dog SHISA9 (96% identical), rabbit SHISA9 (96% identical), guinea pig SHISA9 (95% identical), pig SHISA9 (95% identical), rat Shisa9 (94% identical), mouse Shisa9 (94% identical), tropical clawed frog shisa9 (61% identical). Paralogues in human: SHISA6 (29% identical), SHISA8 (28% identical), SHISA7 (27% identical).
Diseases named in the same sentence as SHISA9 in open-access papers:
SHISA9 is named in the same sentence as 12 diseases in open-access papers, as found by Europe PMC text mining. Sharing a sentence is not in itself a finding about the gene and the disease. The quoted sentences say what the papers report.
schizophrenia (4 papers, 2021 to 2025). A major psychotic disorder characterized by abnormalities in the perception or expression of reality. "We identified two new schizophrenia risk loci, including associations in SHISA9 (rs7192086, P = 4.92 × 10-08) and PES1 (rs57016637, P = 2.33 × 10−11) in Han Chinese population." (PMID 34380480, 2021). "A search in the GeneCards database revealed that SHISA9 may be involved in the regulation of AMPA receptor activity and short-term neuronal synaptic plasticity and was identified as a risk gene for schizophrenia." (PMID 36358398, 2022).
ependymoma (1 paper, 2024). A WHO grade II, slow growing tumor of children and young adults, usually located intraventricularly. "BST1, FLG, KANK4, and SHISA9 were significantly higher expressed in SP-EPN subtype A compared to all other ependymomas, whereas AK5, CFTR, RASSF6, and TBX22 showed high expression in subtype B." (PMID 38265489, 2024).
lung carcinoma (1 paper, 2025). "Given the interplay between mRNA export and autophagy, the interaction of TRIM27, FYTTD1, SHISA9 and pack‐years of smoking may influence autophagy and, in turn, affect lung cancer prognosis." (PMID 39630602, 2025). "Thus, it is plausible that SHISA9 interacts with TRIM27, KIAA0226 and smoking, influencing the autophagy process and ultimately affecting lung cancer prognosis." (PMID 39630602, 2025).
major depression (1 paper, 2021). "Interestingly, Shisa9, which has opposite functions to Shisa6 at glutamatergic synapses, was identified as a highly associated gene for major depression in recently published large-scale GWAS studies." (PMID 34253865, 2021). "Interestingly, Shisa9 was recently identified as a gene related to major depression by large-scale GWAS and is known to counteract Shisa6." (PMID 34253865, 2021).
metabolic syndrome (1 paper, 2025). A cluster of metabolic risk factors for CARDIOVASCULAR DISEASES and TYPE 2 DIABETES MELLITUS. "Of the 22 female-specific MDD/metabolic syndrome pleiotropic regions, possible causal risk loci mapped to multiple genes (GPC6, SHISA9, RP11-154H12.3, KCNG2, TXNL4A, RBFA and ADNP2)." (PMID 40858613, 2025).
psychosis (1 paper, 2024). "A subset of 38 GWAS genes was common to all psychiatric disorders considered here; this includes genes such as GRIN2A, DGKI and SHISA9, which were previously known to be involved in multiple psychosis." (PMID 38864245, 2024).
Tinnitus (1 paper, 2022). Tinnitus is an auditory perception that can be described as the experience of sound, in the ear or in the head, in the absence of external acoustic stimulation. "In summary, the genomic region involving SHISA9 might influence synaptic plasticity contributing to tinnitus perception." (PMID 36581688, 2022).
SHISA9 also shares sentences with these, for which no sentence is quoted: Barrett esophagus (1 paper); epilepsy (1); left ventricular hypertrophy (1); psychiatric disorder (1); Theileriosis (1).